IL6 (interleukin 6)
Diseases named in the same sentence as IL6 in open-access papers (continued):
Sharing a sentence is not in itself a finding about the gene and the disease.
sleep disorder (continued). "The mechanism may involve preoperative pain control, which can help reduce perioperative IL-6 levels and hs-CRP levels, alleviate postoperative pain and improve sleep disorders." (PMID 40454146, 2025). "Notably, IL-6 and TNF are key molecules in the interactions between sleep and neuroinflammation and have been found to be elevated also in several sleep disorders." (PMID 37465321, 2023). "In this study, the concentrations of IL-6, TNF-α, and IL-10 were monitored before and after operation in patients with sleep disorders at different time points, to observe the relationship between sleep disorders and the level of cytokines." (PMID 36570021, 2022). "Results of the correlation analysis showed negative correlations between 25(OH)D and glycolipid metabolic parameters (HbA1c, FPG, PBG), depressive symptomatology (assessed by CES-D sum score), sleep disorders (assessed by PSQI sum sores), and three inflammatory markers (CRP, IL-6, sTREM1)." (PMID 36619542, 2022). "EDS, the cardinal symptom of OSAS, may be mediated by cytokines, and EDS patients with sleep disorders such as OSAS, narcolepsy, and idiopathic hypersomnia often have high levels of IL-6 and TNF-α cytokines." (PMID 24895539, 2014).
bipolar disorder (92 papers, 2011 to 2026). A disorder of the brain that causes unusual shifts in mood, energy, activity levels and the ability to carry out day-to-day tasks. "Higher IL-6 levels in childhood were associated with adult hypomania features in a dose–response fashion." (PMID 27476619, 2017). "The finding of an association between IL-6 and features of hypomania echoes the results from a previous study from the ALSPAC cohort that reported an association between childhood IL-6 and depressive and psychotic symptoms at the age of 18 years." (PMID 27476619, 2017). "Increased serum inflammatory biomarkers, including COX-2, arachidonic acid, IL-6, and tumor necrosis factor-alpha, have been observed in patients with bipolar disorder." (PMID 41205479, 2025). "Elevated IL-6 and CRP levels have been associated with the pathophysiology of both unipolar and bipolar disorders, indicating systemic inflammation as a common characteristic in these conditions." (PMID 38785543, 2024). "In bipolar depression, the intricate relationship of zinc, albumin, IL-6, and CRP with the symptoms assessed using the HAMD-17 and MADRS scales reveals a more complex interaction." (PMID 38785543, 2024). "Both unipolar and bipolar disorders exhibit similar profiles in key inflammatory markers, IL-6 and CRP." (PMID 38785543, 2024). "Elevated levels of IL-6 in blood have been found in patients with bipolar disorder, most strongly during the acute mania phase." (PMID 38336728, 2024). "A systematic review of cytokine profiles in patients with bipolar disorder suggested that several cytokines (e.g., sIL‐2R, IL‐6) are “state‐related” markers in medication‐free bipolar disorder." (PMID 34590391, 2022). "Meta-analyses have shown higher levels of pro-inflammatory and anti-inflammatory cytokines, TNF-α, IL-1β, IL-6, IL-4, and IL-10 in patients with bipolar disorder compared to controls at baseline." (PMID 36704001, 2022). "Ex vivo studies using peripheral blood monocytes from patients with bipolar disorder have also shown that lithium reduces expression of inflammatory genes (IL-6, TNF, CXCL2) and decreases IL-6 and IL-1β production." (PMID 36704001, 2022). "Similar to our findings, high basal levels of IL-6 predicted antidepressant efficacy of anti-inflammatory agents, including celecoxib and minocycline itself, as showed in a 6-week trial in bipolar depression." (PMID 33504955, 2021). "Interleukin-6 (IL-6), a pro-inflammatory cytokine, is increased in patients with bipolar disorder in plasma samples, imaging studies and postmortem tissue and is an indicator for an inflammatory state." (PMID 33683478, 2021). "Regarding later stages of bipolar disorder, recent studies have reported higher levels of TNF-alpha and IL-6 in late stages of bipolar disorder." (PMID 30555363, 2018). "A meta-analysis of 30 studies that included 1351 individuals with bipolar disorder and 1248 controls found that plasma/sera levels were elevated for IL-6, TNF-α, soluble IL-2 receptor, IL-4, IL-10, IL-1 receptor antagonist, and soluble TNF receptor-1." (PMID 29803226, 2018). "Moreover, accumulating evidence from numerous reports converges to suggest that IL-6 levels are frequently elevated in individuals diagnosed with either MDD or bipolar disorder." (PMID 41561993, 2025). "The finding that IL-6 levels are significantly elevated in both the manic and euthymic phases of bipolar disorder compared to healthy controls suggests that the disease has an inflammatory component, with inflammation playing a role across all phases of the disorder." (PMID 39941474, 2025). "In persons who have MDD and bipolar disorder, for instance, elevated proinflammatory cytokines, including interleukin-6 (IL-6) and tumor necrosis factor-alpha (TNF-α), have been detected, suggesting that gut-derived inflammation has a part to play in mental health conditions." (PMID 40255763, 2025).
bipolar disorder (continued). "Anti-inflammatory treatment strategies may be helpful in the management of bipolar disorder, and reducing IL-6 levels could be targeted." (PMID 39941474, 2025). "Noteworthy findings include associations of DRD3 with IL6 and TP35 in chronic alcoholic intoxication, alongside implications of DIO1 (a selenium target), DIO2, and DRD3 in thyroid diseases and bipolar disorders, hinting at potential connections to pathways involving exercise and ROS." (PMID 39635461, 2024). "However, the authors did not assess the serum level of inflammatory markers in the euthymic state, the results showed a significant decrease in IL6 level during bipolar depression and severe bipolar mania and decrease in IL10 level during bipolar depression." (PMID 38036661, 2024). "In addition, the decrease of the ratios of IL-6/IL-10 and IL-17/IL-10 found in this study also suggests that immune-inhibition is prominent in bipolar depression, especially in severe BD." (PMID 36741577, 2022). "Several prior studies have associated bipolar disorder with altered concentrations of IL-1 receptor antagonist and IL-6, which in our results did not quite reach statistical significance in both cohorts when controlling for relevant covariates." (PMID 35136035, 2022). "Patients with bipolar disorder have elevated peripheral levels of IL-6 and TNF." (PMID 34610039, 2021). "Moreover, mood stabilisers such as lithium and valproate suppressed IL-6 levels in patients with bipolar disorder compared to untreated patients." (PMID 39296317, 2021). "Our results showed that IL-6, sTNF-R1 in particular may contribute to greater GM reductions in bipolar disorder in comparison to UD patients." (PMID 32000805, 2020). "In addition, some systematic review studies have suggested the possibility of an alteration in several inflammatory cytokines, including TNF-α and IL-6, among patients with bipolar disorder." (PMID 30114239, 2018). "Based on published values, the IL-6/IL-10 ratio is 1:18 in mania and 2:44 in bipolar depression." (PMID 25202283, 2014). "Finally, the comparisons of our findings with other literature have identified some potential biomarker differences between specific mood phases in bipolar disorder from other major mental illnesses that can present similarly, such as IL-6 in and hsCRP in unipolar and bipolar depression." (PMID 30113291, 2018). "Individuals with bipolar disorder presented significantly higher levels of CK-MB (p = 0.0016), CRP (p < 0.0001), IL-6 (p = 0.0198), and IL-1β (p = 0.0067)." (PMID 41750331, 2026). "In contrast, another population-based study showed significantly higher serum IL-6 and IL-10 levels in patients with MDD or bipolar disorder (BD) than in a healthy control group." (PMID 38646609, 2024). "Serum levels of IL-6, IL-10, TNF-α, and MDA were also improved in patients with bipolar disorder treated for 8 weeks with a specific mix of lactic probiotics." (PMID 37764004, 2023). "Atypical antipsychotics, which are used as a treatment for both MDD and bipolar disorder, have also been shown to decrease levels of TNF-α and IL-6 in animal models." (PMID 39296317, 2021). "Biomarker meta-analyses suggest a combination of high-sensitivity C-reactive protein/interleukin-6, brain derived neurotrophic factor/tumour necrosis factor (TNF)-α and soluble TNF-α receptor 1 can differentiate specific mood phase in bipolar disorder." (PMID 30113291, 2018). "Because SED is conceptualized as a transdiagnostic endophenotype among ADHD and major affective disorders, we investigated the effects of both diagnoses (ADHD and major affective disorders) and SED on MMP-9, CRP, and IL-6 levels and on inhibitory control function." (PMID 40219625, 2025). "Additionally, the levels of IL-6, IL-8, TNF-α, and IL-4 were found to increase during the acute manic phase of bipolar disorder." (PMID 38807424, 2024).
bipolar disorder (continued). "In particular, in the study by Savitz and colleagues, participants with bipolar depression who responded to minocycline had significantly greater decreases of IL-6 over 6 weeks of treatment when compared with non-responders." (PMID 33504955, 2021). "Most significantly, a combination of hsCRP/IL-6, BDNF/TNF-α and sTNFR1 may offer the potential to differentiate people with bipolar disorder from matched controls specific to bipolar mood phase." (PMID 30113291, 2018). "hsCRP and IL-6 are raised in both euthymia and mania but are not significantly different from controls in bipolar depression." (PMID 30113291, 2018). "However, no other relationships were found among IL-6, IL-8, and CRP levels and the clinical features of unipolar and bipolar depression." (PMID 30762747, 2019). "However, GFAP did not correlate with peripheral interleukin‐6 (IL‐6) or total antioxidant capacity (TAC), suggesting that peripheral and CNS inflammation may contribute to the pathophysiology of bipolar disorder in distinct ways." (PMID 40265626, 2025). "However, despite ICV injection of ouabain 10 mM in rats mimicking some aspects of bipolar disorder, ouabain injection does not increase the inflammatory molecules that are present in bipolar disorder patients, with ICV injection of high-dose OUA decreasing striatal IL-6 levels." (PMID 26909067, 2016).
Glucose intolerance (92 papers, 2010 to 2025). Glucose intolerance (GI) can be defined as dysglycemia that comprises both prediabetes and diabetes. "Fecal Bifidobacteria levels were inversely associated with glucose intolerance and inflammatory biomarkers, including IL-1β, IL-6, TNF-α and MCP-1." (PMID 33922965, 2021). "Our previous publication also showed that normal diet-fed wild-type mice develop glucose intolerance after adoptive transferring with HGK-deficient IL-6-producing T cells." (PMID 26918832, 2016). "The present study shows that footshock-stress caused a glucose intolerance accompanied by an increase in corticosterone level and IL-6 epididymal protein content." (PMID 21569357, 2011). "Footshock-stress promotes glucose intolerance associated to corticosterone serum level and epididymal white adipose tissue IL-6 concentration increase." (PMID 21569357, 2011). "In summary, footshock-stress promoted glucose intolerance associated to corticosterone serum level and epididymal white adipose tissue IL-6 concentration increase." (PMID 21569357, 2011). "IPA suggested four upstream regulators that could be linked to glucose intolerance: interleukin 6 (IL6), tuberous sclerosis complex 2 (Tsc2), peroxisome proliferator-activated receptor gamma coactivator 1-beta (Ppargc1b), and lysine (K)-specific histone demethylase 1A (Kdm1a)." (PMID 35377872, 2022). "In AD mouse models (APPswe/PS1ΔE9), neutralisation of IL-6 in the brain improved memory performance, corrected peripheral glucose intolerance and reduced circulating IL-6 levels." (PMID 41009474, 2025). "Proteobacteria and Desulfovibrionaceae exhibited significant positive correlations with pro-inflammatory markers (TNF-ɑ and IL-6), glucose intolerance (GTT AUC), and branched-chain keto acid (BCKA) levels." (PMID 40415947, 2025). "Neutralization of IL-6 and suppression of the signal transducer and activator of transcription 3 signaling in the brains of AD mouse models reduced memory impairment and peripheral glucose intolerance and normalized plasma levels of IL-6." (PMID 40379890, 2025). "In parallel, blocking IL-6 trans-signaling in the paraventricular nucleus of the hypothalamus enhances feeding and glucose intolerance." (PMID 38136564, 2023). "Neutralization of IL-6 and inhibition of the signal transducer and activator of transcription 3 (STAT3) signaling in the brains of AD mouse models alleviated memory impairment and peripheral glucose intolerance, and normalized plasma IL-6 levels." (PMID 33911072, 2021). "We previously reported that the mRNA and protein levels of IL-6 were elevated in the liver of Ncoa5+/− male mice and that heterozygous deletion of Il-6 gene rescued glucose intolerance and hindered HCC development in Ncoa5+/− male mice." (PMID 31664153, 2019). "To examine the role of STAT3 and TLR4 in the development of glucose intolerance, we tested IL-6-induced insulin-stimulated uptake of 2-NBDG in the skeletal muscle." (PMID 28706484, 2017). "We observed improvement in IL-6-induced glucose intolerance by RNAi-mediated silencing of STAT3, suggesting that silencing of the STAT3 gene exerts positive effects on glucose homeostasis." (PMID 28706484, 2017). "To confirm that glucose intolerance is induced by prolonged IL-6 exposure, we evaluated glucose uptake after IL-6 treatment for 2, 24, 48, and 72 h." (PMID 28706484, 2017). "IL-6 worsened glucose intolerance compared with vehicle-treated mice in both genotypes." (PMID 40864559, 2025). "Furthermore, neutralizing IL-6 in the brains of AD mice had a concomitant beneficial effect on their memory, peripheral glucose intolerance, and systemic IL-6 levels." (PMID 40606939, 2025). "Additionally, downregulating IL-6 expression alleviates glucose intolerance, a common dysfunction exaggerated by IL-6 in AD progression." (PMID 38891990, 2024).
Glucose intolerance (continued). "In addition, conditional loss of the calcitonin receptor (Calcr) in proopiomelanocortin (POMC) neurons of the hypothalamus leads to increased body weight gain, increased adiposity, and glucose intolerance as a result of microglial IL-6 release." (PMID 36890585, 2023). "Finally, inhibition of brain STAT3 signaling by i.c.v. treatment with AG490 normalized peripheral glucose tolerance in AβO-infused mice, and i.c.v. treatment with anti-IL-6 reversed glucose intolerance in APP/PS1 mice." (PMID 33911072, 2021). "IL-6 has been reported as a regulator of energy and glucose metabolism, which may contribute to the lower weight gain and lesser degree of glucose intolerance observed in females than males when on HFD for a short period of time." (PMID 34439950, 2021). "Later, it was found that the loss of IL-6, not only failed to protect against these deleterious effects, but also induced glucose intolerance leading to development of mature-onset obesity." (PMID 28429777, 2017). "Additionally, mice that globally lack IL-6 or IL-6 receptor expression in the liver develop glucose intolerance." (PMID 22962620, 2012). "The exact role of the opposite effects and clinical impact of p-TNF-α and p-IL-6 on loss and gain of body weight and indirectly on the development of glucose intolerance is not known." (PMID 20529356, 2010). "Additionally, the knockout of tissue inhibitor of metalloproteinase 3 (Timp3) triggers liver steatosis and glucose intolerance due to induced dysbiosis and systemic inflammation via interleukin 6 (IL-6) signaling, with antibiotic treatment ameliorating these effects." (PMID 39791180, 2025). "Thus, our findings pointing to increased glucose, triglycerides, and glucose intolerance observed in the OB group may be related to decreased adiponectin and increased IL-6, TNF-alpha, and PAI-1." (PMID 28878683, 2017). "PCBs increase tumour necrosis factor-alpha (TNF-α) and interleukin-6 (IL-6), BPA decreases serum adiponectin levels and increases serum IL-6 and TNF-α, leading to IR and glucose intolerance." (PMID 41488239, 2025). "Continuously elevated levels of IL-6 and TNF-alpha can disrupt carbohydrate metabolism, resulting in glucose intolerance and gestational diabetes mellitus." (PMID 36993820, 2023). "In addition, at 3 months of age, IL-6 knockout mice showed an impaired exercise capacity and glucose intolerance, and they became obese by 9 months; however, these anomalies were linked to decreased levels of AMPK, making it unclear whether IL-6 was the causative factor." (PMID 35563026, 2022). "Here, we demonstrated that central acute blockade of IL-6 rescued glucose intolerance, plasma IL-6 concentration and memory performance in APP/PS1 mice, indicating a central role of IL-6 in memory and metabolic dysregulations in AD71,72." (PMID 33911072, 2021). "Glucose intolerance was partially prevented by L. kefiri treatment (GTT) and local inflammation (TNFα; IL1β; IL6 and INFγ) was completely inhibited in EAT." (PMID 28513533, 2017). "The main finding of this study was that, prolonged (24 h) exposure of IL-6 mediates TLR4 gene expression via STAT3-SOCS3 activation and induces glucose intolerance and inflammation in the skeletal muscle." (PMID 28706484, 2017). "HFD-fed Sfrp5-deleted mice exhibited accumulation of macrophages (F4/80 and CD68), c-Jun NH2-terminal kinase (JNK) activation, an increase in proinflammatory mediators (TNF-α, IL-6, monocyte chemotactic protein-1 (MCP-1), severe glucose intolerance, and hepatic steatosis." (PMID 28661198, 2018). "Inflammation can also lead to other pregnancy complications, elevated levels of the pro-inflammatory cytokines Interleukin-6 (IL-6) and Tumour Necrosis Factor—alpha (TNF-α) for example interfere with insulin signalling and lead to glucose intolerance resulting in gestational diabetes mellitus." (PMID 25806806, 2015).
Glucose intolerance (continued). "We provided novel evidence suggesting that poorer running capacity in IL-6−/− mice is not due to lower V′O2max, impairment of peripheral endothelial function, glucose intolerance or impaired muscle oxidative capacity." (PMID 24533077, 2014). "Pharmacological inhibition of mTORC1 with rapamycin in HFD-fed mice worsened glucose intolerance and AT inflammation by increasing the number of polarized M1 macrophages, naive and activated cytotoxic T lymphocytes, and proinflammatory markers such as TNF-α, IL-6, and MCP-1." (PMID 28661198, 2018).